TTK (TTK protein kinase)
Diseases named in the same sentence as TTK in open-access papers (continued):
Sharing a sentence is not in itself a finding about the gene and the disease.
breast carcinoma (continued). "Mono-polar spindle 1 (Mps1/TTK) represents a protein kinase reported to be vital for cell division processes and is generally regarded as an attractive target for the treatment of hepatocellular carcinoma, breast carcinoma, and colon cancer." (PMID 29925769, 2018). "Therefore, TTK plays a special and complicated role in breast cancer and should be regarded as an important regulator factor." (PMID 27833085, 2016). "Elevated TTK mRNA levels are found in several human cancers, including thyroid carcinoma, breast cancer, lung cancer, pancreatic cancer, prostate cancer, and melanoma, as well as glioblastoma and hepatocellular carcinoma—where it is associated with poor prognosis." (PMID 27833085, 2016). "Thus, TTK presents a potential biomarker to predict patient prognosis in breast cancer or as a useful drug target for a subset of breast cancers." (PMID 25278993, 2014). "In addition, TTK belongs to a list of 16 kinases overexpressed in TNBC in comparison to LA breast cancers." (PMID 23700430, 2013). "Many studies have shown a connection between high TTK expression and malignant progression in different types of cancer, including pancreas cancer, gastric cancer, colon cancer, clear cell renal cell carcinoma, prostate cancer, breast cancer, non-small-cell lung cancer, and medulloblastoma." (PMID 38410481, 2024). "Moreover, selective TTK inhibitors have been shown to inhibit tumor growth in vivo models and improve overall survival with little to no toxicity when combined with docetaxel in animal models of breast cancer." (PMID 38886738, 2024). "In addition, accumulating evidence indicates that TTK is related to poor prognosis and malignant progression in gastric cancer, colon cancer, clear cell renal cell carcinoma, prostate cancer, breast cancer, non-small-cell lung cancer, and medulloblastoma." (PMID 35850753, 2022). "In the present study, we evaluated mRNA expression patterns of the mitotic kinases Nek2, Mps1/TTK, and TBK1, as well as the expression and association of these proteins with biomarkers of proliferation (Ki67) and EMT (E-cadherin and Vimentin) by using a novel breast cancer TMA." (PMID 36494865, 2022). "However, high expression levels of TTK could be detected in different types of cancer, including glioblastoma, esophageal cancer, and breast cancer." (PMID 34187556, 2021). "We previously reported silencing TTK could decrease CA in HER2+ breast cancer cell lines." (PMID 30206215, 2018). "This investigation aims to assess TTK protein expression in treatment‐naïve pre‐treatment cores and paired pre‐ and post‐NACT breast cancer (BC) cohorts, as well as its correlation with microcephaly 1 (MCPH1) protein expression." (PMID 39775836, 2025). "GEPIA analysis disclosed that breast cancer patients have significantly higher expression of AURKA (4.0 vs. 1.5), AURKB (4 vs. 1), TTK (2.5 vs. 0.5), MELK (3.0 vs. 0.5), KIF20A (3.5 vs. 0.5) genes compared to healthy people." (PMID 37231064, 2023). "The usage of bioinformatics tolls resulted in the identification of AURKA, AURKB, TTK, MELK and KIF20A as top 5 hub genes involved in breast cancer occurrence and progression." (PMID 37231064, 2023). "We examined the TCGA dataset to understand the differences in the mRNA expression of Nek2, TTK, and TBK1 in NHW (n = 743), NHB (n = 187), and H/L (n = 39) populations with breast cancer based on their self-reported race and ethnicity." (PMID 36494865, 2022). "Previous studies analyzing TTK expression from breast cancer biopsies for each of the main breast cancer subtypes including TNBC, Her2, Luminal A, and Luminal B found that TTK overexpression was specific for the TNBC subtype." (PMID 36494865, 2022). "In addition, high expression of TTK was positively correlated with higher invasiveness and treatment resistance of breast cancer, suggesting that TTK may be involved in cancer cell proliferation and poor patient survival, and is an independent prognostic factor." (PMID 35860256, 2022).
breast carcinoma (continued). "The novel prognostic SLEscore with five key therapeutic targets (RACGAP1, HMMR, TTK, TOP2A, and KIF15) was developed for the management of breast cancer patients with SLE using the LASSO algorithm." (PMID 36726984, 2022). "This analysis indicates that the mRNA levels of multiple mitotic regulators, including TTK, Nek2, PLK1, Cyclin B1, BUB1, Aurora kinases A and B, and NDC80 (also known as HEC1) are elevated in breast cancers in NHB women." (PMID 36494865, 2022). "Many studies have shown that TTK is overexpressed in several human malignant tumours, including malignant melanoma (MM), non-small cell lung carcinoma (NSCLC), prostate cancer, breast cancer, and colon cancer." (PMID 33282948, 2020). "More convincingly, the result of qRT-PCR using breast cancer tissues and matched paracancerous tissues exhibited a significant upregulation of ASPM, CDC20, and TTK in breast cancer compared to paracancerous tissues (P < 0.001)." (PMID 31106147, 2019). "Recent studies have demonstrated that kinases involved in the formation of the mitotic spindle, such as TTK/Mps1, polo-like kinases (PLKs) or NIMA/NEK2, are overexpressed in this particular breast cancer subtype." (PMID 28108739, 2017). "By contrast, only 31.26% of the promoters of coding genes were aberrantly methylated in breast cancer, some of which were in known disease-related genes, such as HOXB2, FGF4 and TTK." (PMID 25739977, 2015). "Specifically, breast cancer cells overexpressed GINS2, TTK, CEP192, and shugoshin 1 and have lower levels of C-Nap1, semaphorin 6A, MDM2 and SFRP1." (PMID 25278993, 2014). "Moreover, studies showed a significant correlation between TTK overexpression and HER2‐positive breast cancer." (PMID 39775836, 2025). "Based on available clinical information, it appears that TTK inhibitors have been mainly investigated in solid tumors and breast cancer subtypes, like TNBC, but patients have not been otherwise selected." (PMID 39184047, 2024). "Moreover, some genes, such as TTK and MELK, were repeatedly observed in various PAM50 subtypes of primary mammary carcinoma and even in bone-metastatic and skin-metastatic breast cancer." (PMID 37231064, 2023). "Since the cell cycle is one of the most commonly deregulated cellular processes in cancer, we propose that the mitotic kinases TTK (or Mps1), TBK1, and Nek2 could be novel targets to prevent breast cancer progression among NHBs and H/Ls." (PMID 36494865, 2022). "Additionally, CENPE, TOP2A, CENPF, TTK, and NDC80 are highly expressed in the cell cycle of basal-like breast cancer." (PMID 35496042, 2022). "To address whether our observations in mammary epithelial cells are translated into breast cancers, we performed TCGA analysis on selected SAC proteins, including BubR1, NDC80, Sgo1, and Mps1/TTK in relation to E2Fs genes using cBioPortal." (PMID 29100415, 2017). "In this report, we show for the first time that attenuating TTK levels can decrease the percentages of CA observed in a subset of Her2+ breast cancer cells without affecting the integrity of DNA synthesis." (PMID 25278993, 2014). "Despite the general overexpression of Nek2 and TTK shown in breast cancer, no clear information exists on whether this is a general or specific pattern related to the genetic context of patients." (PMID 36494865, 2022). "Such mechanistic insight into how TTK mediates EMT could facilitate the study of TTK expression as a biomarker for tumor aggressiveness in the context of TGF-β signaling and treatment responses in breast cancer patients." (PMID 30206215, 2018). "TTK and Nek2 are significantly overexpressed in NHB women with breast cancers that do not fall within any specific molecular classification, or that failed to classify (other)." (PMID 36494865, 2022).
breast carcinoma (continued). "For example, in patients with early breast cancer of hormone receptor positive and HER2 negative, a high level of TTK expression predicts a good survival and may spare adjuvant chemotherapy safely." (PMID 27833085, 2016). "Kinases BUB1, CHEK1, IRAK1, TTK, RYK, and VRK2, identified in this study, for example, have been reported to be highly overexpressed in ER-negative breast tumors and were critical for the growth of either ER-negative only or both ER-positive and -negative breast cancer cells." (PMID 22309939, 2012).
lung carcinoma (22 papers, 2013 to 2025). "TTK’s role in preserving genomic integrity is crucial, with its irregularities associated with various cancers such as breast, liver, and lung cancers." (PMID 37894942, 2023). "TTK’s potential diagnostic and prognostic importance has been reported in thyroid cancer, triple-negative breast cancer, and different types of lung cancer." (PMID 37304238, 2023). "A higher histological stage, a greater number of metastatic lymph nodes, and a shorter 5-year overall survival in lung cancer are all linked to high TTK expression." (PMID 36829176, 2023). "TTK has been also reported that upregulation of TTK increases lung cancer progression due to X-linked deubiquitinase USP9X dysfunction." (PMID 32121246, 2020). "Therefore, the expression of TTK in tumor tissue may serve as a biomarker for predicting metastatic risk in lung cancer." (PMID 32121246, 2020). "The dual TTK/CLK2 inhibitor CC-671 provides a theoretical basis for overcoming ABCG2-mediated MDR in lung cancer patients." (PMID 38195567, 2024). "Its expression is related to the neuroendocrine differentiation of lung cancer, and it is a determinant of lung cancer invasiveness and prognosis, and TTK mediates the carcinogenic effect of LMO1 in lung cancer cells." (PMID 35784389, 2022). "The long-term cancer growth carried out by colony formation revealed TTK knocking down reduced lung cancer cell proliferation." (PMID 32121246, 2020). "Although further exploration is required to clarify the underlying molecular mechanism how TTK regulates DPYSL3 expression and then potentiates malignant behavior, our study offers a valuable insight for the specific management patients with lung cancer." (PMID 32121246, 2020). "The objective of the study herein illustrates the functional consequences and molecular mechanism of the TTK expression in lung cancer and evaluates its potential significance regarding the beneficial vulnerabilities of lung cancer therapy." (PMID 32121246, 2020). "WST-1 analysis further confirmed TTK knockdown suppressed lung cancer cells proliferation after 3 days’ culture." (PMID 32121246, 2020). "TTK is a serine/threonine kinase that controls the cell proliferation through mitosis by modulating the SAC, we thus silenced TTK expression by shRNA plasmid transfection in lung cancer for investigating the role of TTK in lung cancer growth." (PMID 32121246, 2020). "To prove the role of TTK involving in lung cancer, we assessed the expressions of TTK from normal and cancer parts of two lung cancer patients." (PMID 32121246, 2020). "The correlation of DPYSL3 and TTK expression was also observed in the sequential tissue section of tumor part of lung tissue obtained from patients with lung cancer." (PMID 32121246, 2020). "Next, we assessed the role of TTK on lung cancer metastasis, control and TTK-knockdown A549 were injected into mice via the tail vein as a metastasis model." (PMID 32121246, 2020). "Our previous study showed that elevated levels of TTK were found in the tumor parts of lung cancer using NGS." (PMID 32121246, 2020). "Here, we found that TTK was upregulated in the tumor tissue of patients with lung cancer, and enhanced tumor growth and metastasis in vitro and in vivo." (PMID 32121246, 2020). "We provide the first identification that TTK acts as a downstream mediator of LMO1 function in lung cancer cells." (PMID 30038707, 2018). "Consistent with the observed over-expression in lung tumor specimens relative to NATs, our investigation in a panel of cell lines showed that TTK mRNA was over-expressed in lung cancer cell lines relative to immortalized normal HBEC cells." (PMID 30038707, 2018). "Taken together, these results suggest that TTK plays a key role in mediating the oncogenic function of LMO1 in lung cancer cells." (PMID 30038707, 2018).
lung carcinoma (continued). "Over-expression of LMO1 with pcDNA3.1-Flag-LMO1 expression vector significantly up-regulated expression of TTK mRNA as compared with cells transfected with empty vector pcDNA3.1 in six of the seven lung cancer cell lines tested." (PMID 30038707, 2018). "By combining gene expression correlations with patient survival and functional in vitro investigations, we further identified TTK as mediating the oncogenic function of LMO1 in lung cancer cells." (PMID 30038707, 2018). "Together, these results support a role for TTK in mediating the function of LMO1 in lung cancer cells." (PMID 30038707, 2018). "Likewise, in other types of lung cancer, heightened TTK expression has been reported to promote cell migration and epithelial-mesenchymal transition (EMT), thereby enhancing metastatic potential and facilitating tumor metastasis." (PMID 38195567, 2024). "At present, some studies have found that TTK may be related to the occurrence and development of lung cancer." (PMID 35784389, 2022). "Also, TTK is a biomarker for prognosis of Non-small cell lung cancer, and the upregulation of TTK increases the cancer progression in lung cancer." (PMID 35520289, 2022). "TAs, such as Survvin, VEGFR (vascular endothelial growth factor receptor), MUC1 (mucin 1) and TTK (TTK protein kinase), were used most extensively as targets for developing peptide‐based therapeutic cancer vaccines, targeting lung cancer, gastrointestinal cancer and melanoma." (PMID 33754407, 2021). "It was found that TOP2A, CCNB1, CCNA2, CDK1, and TTK might be the critical target genes of lung cancer." (PMID 34616430, 2021). "In addition, the five cohorts form Oncomine® database showed that levels of TTK expression were higher in cancer parts than normal parts in lung cancer patients." (PMID 32121246, 2020). "Taking all three datasets, we speculated that TTK might play an oncogenic role in lung cancer development." (PMID 32121246, 2020). "The expression of TTK in lung cancer tissues is significantly different from that in smokers and non-smokers, which is consistent with the important role of TTK in smoking-induced lung cancer." (PMID 31726467, 2019). "TTK is a candidate target gene for chemical prevention and treatment of lung cancer in smokers." (PMID 31726467, 2019). "Knock-down of TTK expression by siTTK significantly decreases lung cancer cell survival." (PMID 30038707, 2018). "Also, increased expression of TTK has been observed in various types of lung cancer, which leads to the stimulation of cell migration and the process of epithelial–mesenchymal transition (EMT), ultimately leading to increased metastatic capabilities and facilitating tumor expansion." (PMID 40723362, 2025). "Elevated TTK expression was later described in several other cancers, such as breast, pancreatic, liver and lung cancers, where TTK inhibition induced polyploidy and apoptosis in lung cancer cells, highlighting the therapeutic potential of TTK inhibitors in cancer treatment." (PMID 36980267, 2023). "TOP2A, CCNB1, CCNA2, CDK1, and TTK may be the key target genes of lung cancer." (PMID 34616430, 2021). "We then examined whether TTK knock-down affects lung cancer cell survival and proliferation." (PMID 30038707, 2018). "Some of the predicted master regulators, including PTTG1, RFC4, TRIP13, BUB1B, TTK, and ZWINT are capable of promoting migration, invasion, and metastasis of lung cancer cells." (PMID 36304306, 2022). "TTK and DPYSL3 upregulation was positively correlated with a poor clinical outcome in patients with lung cancer." (PMID 32121246, 2020). "Taken together, our study offers insights into TTK as an oncogene that regulates cell proliferation, movement and EMT in lung cancer." (PMID 32121246, 2020). "In this study, we further demonstrated that TTK enhances cell proliferation, migration, EMT and invasion in lung cancer." (PMID 32121246, 2020).
lung carcinoma (continued). "Together, our findings revealed a novel mechanism underlying the oncogenic potential effect of TTK and clarified its downstream factors NTS and DPYSL3 might represent a novel, promising candidate oncogenes with potential therapeutic vulnerabilities in lung cancer." (PMID 32121246, 2020). "TTK was identified as one of the angiogenic modulators in a robust ESC-based vascular differentiation assay, reducing tumor growth, vascular density, and improving lung carcinoma survival in vivo." (PMID 32121037, 2020). "Using both NGS and bioinformatics approaches to characterize the gene profile of lung cancer, we identified TTK had the oncogenic potential in lung cancer, compared to non-cancerous cells." (PMID 32121246, 2020).